ESR1 (estrogen receptor 1)
Diseases named in the same sentence as ESR1 in open-access papers (continued):
Sharing a sentence is not in itself a finding about the gene and the disease.
breast cancer (continued). "Promoter studies in breast cancer cells indicated that PRSS23 is upregulated by estrogen receptor 1 (ESR1) and that its upregulated expression contributes to cell proliferation." (PMID 34997121, 2022). "To test if such synergy exists in the context of ESR1 mutant breast cancer, we tested OTX015 in combination with abemaciclib, an approved CDK4/6 inhibitor, in MCF-7 Y537S cells." (PMID 35881485, 2022). "Our previous studies demonstrate that these important drug targets in breast cancer, ESR1, PGR, HER2, EGFR, and AR have a high similarity in mRNA and protein variations in both tumors and cell lines." (PMID 36360219, 2022). "Li and colleagues provided detailed evidence supporting the function of ESR1-e2>CCDC170 in promoting breast cancer cell survival and endocrine resistance both in vitro and in xenograft models." (PMID 36686845, 2022). "The local genetic correlation analysis in our study highlighted specific loci at which MD phenotypes and breast cancer showed evidence of shared heritability (DA: ESR1, ZNF365, LSP1, and MKL1; NDA: 8p11.23; PMD: ESR1 and ZNF365)." (PMID 35414113, 2022). "Its expression was closely related to Letrozole resistance in breast cancer therapy Through analysis of 4 databases, 7 miRNAs that can target ESR1 were screened out, and 4 miRNAs that can target CYP19A1 were screened out through bioinformatics analysis." (PMID 35657638, 2022). "From the analysis of the SNPs known to be associated with breast cancer risk, we replicated the previously reported associations with the ATXN1 and ESR1 loci." (PMID 35681745, 2022). "rH/E distinguishes the HER2-enriched subtype breast cancer better than ERBB2 or ESR1 expression alone, which can help to more accurately identify the subgroups of tumor which are predominantly driven by HER2 or ER in the HR+/HER2+ population." (PMID 36620573, 2022). "MYC also represses lineage-specific transcription factors in mammary tissues, such as GATA3 and ESR1 to drive cancer stem cell-like states in breast cancer." (PMID 36207293, 2022). "Up-regulation of ESR1 transcript by this lncRNA has a crucial impact in the proliferation of ESR-positive breast cancer." (PMID 36467407, 2022). "Through analysis of RNA-sequencing data in breast cancer, recurrent intragenic fusions of 5′ end of ESR1 and the 3′ ends of AKAP12, ARMT1 or CCDC170 amongst other genes have been identified." (PMID 35151276, 2022). "ESR1 (Estrogen Receptor 1) overexpression is observed in 60–70% of the human breast cancers, and the hyper-activation of the Estrogen signaling pathway provides proliferative advantages, as well as the metastatic potential to the cancer cells." (PMID 35273218, 2022). "When first described, ESR1-e2>CCDC170 in ER+ breast cancer cells led to enhanced growth and reduced sensitivity to tamoxifen suggesting a role for ESR1-e2>CCDC170 in ET resistance." (PMID 36686845, 2022). "In breast cancer (BC), recurrent fusion genes of estrogen receptor alpha (ESR1) and AKAP12, ARMT1 and CCDC170 have been reported." (PMID 35151276, 2022). "As a result, endocrine therapy has been and still is a successful treatment in patients with ESR1-positive (ESR1 +) breast cancers (BC)." (PMID 35151276, 2022). "The authors showed that, although menin possesses a crucial tumor-suppressive role in normal mammary cells, it acts as an oncogenic factor in ERα + breast cancer cell lines through an enhancer-mediated regulation of ESR1 transcription." (PMID 34561764, 2021). "Every woman with breast cancer has the ESR1 gene but in only 70–80% of breast tumours is ERα expressed, as shown by immunohistochemistry." (PMID 34930150, 2021).
breast cancer (continued). "In our cohort, 2.7% (16/589) of the patients have ESR1 mutations, with 69% (11/16) of the patients harboring ESR1 mutation had stage III breast cancer." (PMID 33968723, 2021). "In MCF7 cells, L1 transposons were found to be bound by a total of 99 TFs, including ESR1, MYC, FOXA1 and E2F1, which have well-established and critical roles in cell growth and division and have been linked to breast cancer development." (PMID 34070697, 2021). "ESR1, or the estrogen receptor, is a major regulatory protein in breast cancer transcriptional regulation." (PMID 34070697, 2021). "Human breast cancer cell lines including T47D, MCF7, and MDA-MB-231 have been extensively studied, and have been engineered to have ESR1 mutations." (PMID 34717714, 2021). "The identification of therapeutic strategies in breast cancers harbouring ESR1 mutants is an area of active interest." (PMID 34499316, 2021). "For instance, a recent study identified a series of lincRNAs called Eleanors (ESR1 locus enhancing and activating noncoding RNAs) that activates the ESR1 locus in breast cancers." (PMID 34906173, 2021). "In the case of breast cancer, the only ongoing studies enrolled mBC patients for ESR1 and HER2 analyses." (PMID 34440110, 2021). "Bazedoxifene is more potent than tamoxifen and fulvestrant in ESR1-MUT breast cancer cells and is effective in tamoxifen-resistant cells and patient-derived xenograft (PDX) models." (PMID 34392831, 2021). "A point-of-care mRNA STRAT4 breast cancer assay for ESR1, PGR, ERBB2, and MKi67, for use on the GeneXpert platform, has been recently validated on tissues from internationally accredited laboratories, showing excellent concordance with IHC." (PMID 34050358, 2021). "Breast cancer-related genes from GAD were also identified as ESR1 interactors, including TP53BP1, SRA1, and BBS4." (PMID 33987091, 2021). "Upregulated mSigDB modules include pathways typically associated with breast cancer invasiveness, including SMARCE1 targets (p-value 2.6E−16), ESR1 targets (p-value 5.3E−16), and a comparison of luminal and mesenchymal breast cancers (p-value 2.1E−12)." (PMID 33413550, 2021). "We compared the efficiency of various proteomic techniques to determine routinely measured breast cancer biomarkers, including ESR1, PGR, HER2, and MKI67." (PMID 34408238, 2021). "Examples of putative breast cancer susceptibility genes identified using eQTL-based approaches include: ABHD8 at 19p13, AKAP12/ESR1 at 6q25.1, and MYC at 8q24." (PMID 34439109, 2021). "GATA3 is known to be a major factor involved in the regulation of ESR1 expression and is ubiquitously present in luminal A breast cancers." (PMID 34561764, 2021). "When compared to other TCGA intrinsic subtype cohorts (HER2, luminal A, and luminal B) and a SMMART-program cohort (40 metastatic breast cancers), AR was moderate, while ESR1 was low." (PMID 33772089, 2021). "Previous studies have shown that ESR1 is closely related to the occurrence and development of various urogenital cancers, especially breast cancer and endometrial cancer." (PMID 33865377, 2021). "In this review, we will focus on the mechanisms known to control ESR1 expression, with a focus on positive regulation by transcription factors expressed in ER+ breast cancer, also called luminal breast cancer." (PMID 34831189, 2021). "In Tam-resistant ESR1 breast cancer cells, NUPR1 depletion results in premature senescence in vitro and tumor suppression in vivo." (PMID 33542201, 2021). "The hyper-methylation status of ESR1 has been reported previously in lung adenocarcinoma, breast cancer, prostate cancer, squamous cell cervical cancer, and CRC." (PMID 34778269, 2021). "ESR1/ER, possibly the marker with both the highest predictive and prognostic value in breast cancer, reached an OPA of 98.9%." (PMID 34371382, 2021).
breast cancer (continued). "Here we identify that NUPR1, a tamoxifen (Tam)-induced transcriptional coregulator, is necessary for the maintenance of Tam resistance through physical interaction with ESR1 in breast cancers." (PMID 33542201, 2021). "This GATA3 mediation is one of the central components of the ESR1 complex that determines the binding potential and transcriptional targets in breast cancer cells." (PMID 33670895, 2021). "Breast cancer clinical treatment selection is based on the immunohistochemical determination of four protein biomarkers: ESR1, PGR, HER2, and MKI67." (PMID 34408238, 2021). "ChIP-qPCR on FOXC1 wt and knock-out BT549 basal-like breast cancer cells showed a correlation between trimethylation of H3K9, FOXC1 expression and loss of RNA PolII recruitment at the ESR1 regulatory sequence." (PMID 34831189, 2021). "Taken together, these results suggest that UBC9 is required for TRIM3 regulation of ESR1 SUMOylation and the promotion of tamoxifen resistance in breast cancer." (PMID 34508066, 2021). "Based on the observed correlation between APTR and ESR1 in the current study, APTR/miR-9/ESR1 is another putative functional axis in breast cancer." (PMID 34094972, 2021). "Nevertheless, it should be remembered that 10% of the overall ESR1+/HER2− breast cancer patients show primary or secondary resistance to this combined therapeutic approach." (PMID 34445095, 2021). "On the one hand, MAGI1 silencing in the MCF7 breast cancer cell line decreases ESR1 mRNA and ERα protein levels, activates PI3K/Wnt signaling, promotes cell proliferation, and reduces apoptosis and epithelial differentiation." (PMID 34503076, 2021). "FOXA1 has been identified as an upstream regulator of ESR1 expression in mouse and human breast cancer cells and as a repressor of basal-like genes." (PMID 34831189, 2021). "On the other hand, miR-129 inhibits breast cancer cell’s self-renewal by suppressing Let-7b expression through directly inhibiting Estrogen Receptor 1 (ESR1)." (PMID 33413418, 2021). "Fulvestrant has shown some efficacy in ESR1-altered ERα-positive breast cancers previously treated with SERMs and continues to be the treatment of choice at present." (PMID 33498407, 2021). "Another explicative example concerning breast cancer is given by the emerging role of ESR1, the gene encoding ERα, part of the estrogen receptor." (PMID 34298675, 2021). "After functional enrichment analysis of hub nodes, three transcription factors that interact with ESR1 in luminal breast cancer cells were filtered for further analyses." (PMID 34094972, 2021). "Despite advances in antiestrogen therapy for patients with ESR1-positive breast cancer, advanced-stage breast cancer remains largely incurable due to therapeutic endocrine therapy resistance and recurrence." (PMID 33542201, 2021). "ESR1, a steroid receptor, plays an important role in regulating tumorigenesis, such as breast cancer." (PMID 34592904, 2021). "To further explore this counterintuitive result, given ESR1 is a master regulator of transcription and a driver of luminal breast cancers, we identified genes that were consistently altered in ESR1-depleted recurrences." (PMID 33407744, 2021). "For instance, ESR1 is well characterized as a factor that promotes cell proliferation in breast cancer." (PMID 34322374, 2021). "Partitioning by ESR1 revealed a best cut off at 34.485, again close to the median expression of 34.09, which is almost identical to the cut off routinely used in breast cancer diagnostics." (PMID 34073233, 2021). "Lasofoxifene, a SERM initially developed for osteoporosis and in that setting found to reduce breast cancer incidence, remarkably was found in vitro to retain efficacy in the presence of ESR1-MUT." (PMID 34392831, 2021). "IL-1β induces tamoxifen resistance in the breast cancer cell model via prompting of Twist1 that propels methylation in the promoter region of the ESR1 gene which in turn reduces the expression of Erα." (PMID 34220337, 2021).
breast cancer (continued). "The ERα is encoded by ESR1 and is a main target of endocrine therapy (ET), which is widely used for both early and metastatic hormone receptor (HR) positive breast cancer treatments." (PMID 33692409, 2021). "Of them, the top risk-associated TFs included well-known breast cancer master regulators, FOXA1, ESR1, and AR, and other related TFs, such as SIN3AK and TCF7l2." (PMID 34518541, 2021). "In conclusion, we demonstrate herein that MIBC subtypes predict pathological response to NAC, indicating strong phenotypic similarities to breast cancer subtypes, including expression patterns of ESR1 and ERBB2." (PMID 34073233, 2021). "First, we individually generated tamoxifen-resistant (TamR) clones derived from three estrogen receptor alpha (ESR1)-positive breast cancer cell lines MCF-7, T-47D, and BT-474 by exposing them to 2 μM Tam for a period of over 15 months." (PMID 33542201, 2021). "Genistein also inhibits the growth of human MCF-7 breast cancer cells at a concentration of 10−5 M, and even potentiates the anticarcinogenic effects of tamoxifen on the growth of ESR1-positive and HER2-overexpressing human breast cancer cells." (PMID 34578926, 2021). "Taken together, Xpert® Breast Cancer STRAT4 mRNA testing for ESR1, PGR, ERBB2, and MKI67 demonstrated good performance when compared to the diagnostic gold standard IHC/ISH." (PMID 34572945, 2021). "In vitro analysis using breast cancer cell lines further identified a mechanism by which ESR1 expression is positively regulated by direct binding of BRCA1 to the ESR1 promoter, being recruited under the regulation of the transcription factor Oct-1." (PMID 35008774, 2021). "Breast cancer subtypes are generally classified based on the expression of the estrogen receptor (ESR1), progesterone receptor (PGR), or the human epidermal growth factor receptor 2 (HER2)." (PMID 33985544, 2021). "Although mutant ESR1 breast cancer cells show resistance to AI, they retain relative sensitivity to fulvestrant, as reported in the phase III soFEA trial (NCT00253422)." (PMID 34771560, 2021). "We detected 465 DTU genes (FDR < 0.01), including 46 cancer-related genes and 10 genes specifically related to breast cancer, including ESR1 and BCL11A." (PMID 34811492, 2021). "As a result, PI3Ki and mTORC1i can be effective in endocrine-resistant and ESR1-MUT breast cancer cells." (PMID 34392831, 2021). "Our analyses provide compelling evidence that ESR1 PvuII is a novel prognostic marker in breast cancer and is also highly predictive of anticancer therapy outcomes." (PMID 34930150, 2021). "In breast cancer, the MSI2 protein level is markedly elevated and promotes the expression of estrogen receptor 1, which facilitates the malignant biological behavior of breast cancer cells." (PMID 34047477, 2021). "A cBioPortal analysis shows ≈50% of breast cancers with genomic aberrations in PIK3CA, AKT1, AKT2, AKT3, and/or ESR1,suggesting relevance of this signaling axis in breast cancer." (PMID 33498407, 2021). "Resveratrol had shown inhibitory activity on STAT3 acetylation, and it consequently reactivated several tumor suppressors’ genes, such as ESR1 in breast cancer and melanoma." (PMID 34942997, 2021). "We also performed GSVA analysis, and the results revealed that C5AR2 was notably associated with metastasis as well as relapse of breast cancer and the upregulation of ESR1, a proven oncogene in breast cancer." (PMID 34595119, 2021). "Taken together, these findings demonstrate that NUPR1 is a novel participant in the development of Tam resistance that maintains breast cancer cells at an elevated autolysosomal state through ESR1-mediated transcription." (PMID 33542201, 2021). "Together, these studies suggest a positive role for FOXA1 in ESR1 up-regulation in ER+ breast cancer cells, with possible cross-talk with several FOX factors." (PMID 34831189, 2021).
breast cancer (continued). "In breast cancer cell lines, it has been reported that OCT1 binds to the promoter region of ESR1 encoding ERα and induces its transcription." (PMID 34768935, 2021). "Molecular targets such as estrogen receptor (ESR1) and human epidermal growth factor receptor 2 (ERBB2) play an important role in breast cancer management and have also been associated with urothelial bladder cancer." (PMID 34073233, 2021). "We additionally compared the expression of E2-regulated genes (the set identified in MCF7 cells by RNA-seq, i.e., 46 upregulated and 2 downregulated genes) in selected groups of breast cancers with different levels of ESR1 and HSF1." (PMID 34783649, 2021). "These included pathways mediating tumor cell proliferation, survival, and invasion as well as several essential molecular pathways that are known to be critical for the pathophysiology of ER+ breast cancers, in particular, the ESR1 and ERBB2 pathways." (PMID 34524841, 2021). "ESR1 is a predictive biomarker that is of therapeutic importance in breast cancer, and this study indicates that it can play a similar role in lung cancer." (PMID 34178945, 2021). "The introduction of very sensitive technologies like droplet digital polymerase chain reaction (PCR) (ddPCR) have enabled the detection of ESR1 mutations in plasma cell free DNA (cfDNA) and in the CTC-derived DNA of breast cancer patients." (PMID 33535614, 2021). "Expression of ABCB1, ABCC2, ABCG2, SLC22A16, and SLCO1A2 was significantly higher in normal breast tissue compared to tumorous tissue, while SLC22A1 and the tumor marker ESR1 showed a significantly higher expression in breast cancer tissue." (PMID 35008681, 2021). "We identified a group of TFs that showed L1-derived binding almost exclusively in MCF7 breast cancer cells, including ESR1, CTCF and MYC." (PMID 34070697, 2021). "CPEB2 is one of the top six genes, together with ESR1, with the strongest correlation with ER+ breast cancer prognosis." (PMID 33670895, 2021). "Taken together, our results demonstrated that TRIM3 modifies the SUMOylation of ESR1 and confers tamoxifen resistance, which provided a novel therapeutic target for breast cancer therapy." (PMID 34508066, 2021). "A variety of targets, such as estrogen receptor α (ERα), are regulated by BRD7 and BRCA1 coordinately in breast cancer, and BRD7 regulates ERα transcription by recruiting BRCA1 and Oct-1 to the promoter of ESR1 (the gene encoding ERα)." (PMID 34671561, 2021). "Various genomic alterations and genomic signatures, including ERBB2 amplification, mutations in PIK3CA, AKT1, and ESR1, and tumor mutational burden (TMB), have become important biomarkers for treatment selection in breast cancer (BC)." (PMID 33968723, 2021). "Accordingly, the depletion of SALL2 decreased ESR1 and PTEN expression, activated the Akt/mTOR signaling, and resulted in estrogen-independent growth and tamoxifen resistance in ERα-positive breast cancer." (PMID 34944911, 2021). "Previous studies have reported that miR-22 represses ESR1 expression in breast cancer and lead to a reduction in estrogen signaling." (PMID 35223452, 2021). "Large-scale gene expression studies of breast cancer cell lines and primary tumor tissue were instrumental in identifying the selective upregulation of FOXA1 in luminal breast cancers and its strong correlation with ESR1 expression." (PMID 34680352, 2021). "Other regulators not discussed in this review include miRNAs; several are capable of targeting the ESR1 3′UTR and some are negatively correlated with ESR1 in breast cancer." (PMID 34831189, 2021). "The data suggest that KIF2C and ESR1, two co-expressed hub genes, are also positively and negatively correlated with the aggressive and metastatic nature of breast cancer, respectively." (PMID 34172056, 2021). "We observed that the top five strongest TF co-occupancy pairs associated with breast cancer risk were FOXA1 + E2F1, FOXA1 + NR2F2, FOXA1 + ESR1, FOXA1 + SIN3, and FOXA1 + TCF12." (PMID 34518541, 2021).